ENSG00000230186 (novel transcript)
Gene: Long non-coding RNA gene on chromosome 1 (143,885,179 to 143,934,791, forward strand). Ensembl gene ENSG00000230186.
Gene Ontology:
Biological process: mRNA 3'-end processing by stem-loop binding and cleavage